CD4 (CD4 molecule)
Diseases named in the same sentence as CD4 in open-access papers (continued):
Sharing a sentence is not in itself a finding about the gene and the disease.
breast tumor (continued). "Moreover, these hub genes were strongly associated with the extent of infiltration of CD4+ T cells, CD8+ T cells, neutrophils, macrophages, and myeloid dendritic cells into breast tumors." (PMID 35819135, 2022). "Furthermore, we demonstrated that IL4-Rα expression on CD4+ T cells was required for the TSLP-induced suppression of PyMttg breast tumor growth." (PMID 35657353, 2022). "In this study, an increase in the CXCL13‐positive ICs in the high HER2‐AAb group indicates that the CXCL13‐positive ICs in the tumor stroma and the follicular CD4‐positive ICs found in the SLOs both stimulated the maturation of B cells and helped them to migrate to the breast tumor stroma." (PMID 33506656, 2021). "CD4+ T cells drive tumor immunity in MMTV-PyMT breast tumors." (PMID 34283809, 2021). "We found that the high concentration of serum HER2‐AAb was associated with the accumulation of B cells, plasma cells, and CXCL13‐positive ICs in breast tumors and of follicular CD4‐positive ICs, which presumably represented Tfh cells, in the axillary lymph nodes." (PMID 33506656, 2021). "We initiated the study with a longitudinal survey of TCR repertoires monitored in the peripheral blood of individual mice that were in the process of spontaneously developing breast tumors; We recovered a subset of T cells based on their CD4+CD62LhiCD44lo markers." (PMID 33465095, 2021). "However, the efficacy was abrogated when treated with perforin inhibitor concanamycin, suggesting that CT exhibited the anti–breast tumor activity mainly by activating CD4+ T cells to secrete perforin." (PMID 32265690, 2020). "In this study, HTS technology and the immune informatics analysis method were used to analyze the composition and characteristics of the CD4+CD25+ T cells CDR3 repertoires in breast tumor tissues, lung metastatic tissues, and spleens from 4T1 tumor-bearing BALB/c mice." (PMID 33029539, 2020). "Breast tumors are commonly infiltrated by Treg, memory CD4+ T cells, and DCs." (PMID 31143539, 2019). "Thus, this corroborates our in-vitro results by showing that tumor infiltrating pDCs derived from human breast tumors are capable of inducing more FoxP3+ CD4+ T cells, as well." (PMID 31440253, 2019). "To detect and phenotype breast tumor specific CD4+ Treg and Tcon cells by flow cytometry, we had previously developed MHC II tetramers (HLADR 04:01 and HLADR 07:01) loaded with MHC-allele restricted peptides derived from the breast tumor associated antigen mammaglobin I." (PMID 28224210, 2017). "Our findings also suggest that CD4+ follicular helper T cells (Tfh) may be prognostic indicators as they are found in the breast tumors." (PMID 27911271, 2017). "Next, we investigated the levels of Tregs within these CD4+ T cells infiltrating breast tumors." (PMID 28388539, 2017). "There is a paucity of published data regarding CD4+ T cells infiltrating breast tumours." (PMID 27777963, 2016). "Taken together, these results show differences in the kinetics of CD4 + and CD8 + T cell proliferation and trafficking in response to ICB treatment and suggest distinct underlying mechanisms to explain the impact of α-PD1 and α-CTLA4 treatment on immunologically “cold” breast tumors." (PMID 38918836, 2024). "Besides the up-regulated expression of CD39 and PD-1, the expanded CD4+ T cells within the breast tumor tissue showed greater levels of CD25, signifying that although they are activated but exhausted and incapable of mounting any tumor-specific immune response." (PMID 35051220, 2022). "Our data so far suggest that naive CD4+ T cells may differentiate into Tregs within breast tumors." (PMID 28290464, 2017). "Immunization with FGF-2 peptides decreased CD4+CD25+FOXP3+ Treg cells and suppressed tumor vascularization and promoted apoptosis in grafted breast tumor mice model." (PMID 39232704, 2024).
breast tumor (continued). "Both anti-IL-6R and anti-PD-L1 significantly suppressed CD4(+)/CD25(+) Tregs but outscored IgG2b, κ in the infiltration of CD8(+) CTLs in the recurrent breast tumors, suggesting the effective anti-tumor immunity." (PMID 38505617, 2024). "To determine the effects of TOP2A vaccine treatment on different T cell subsets, we performed deep clustering of CD8 + T cells, CD4 + T cells and DNT cells from mouse breast tumors of 3 of 11 mice that had tumors (8 mice were tumor-free)." (PMID 37880313, 2023). "Specifically, it increased the infiltration of CD4+ and CD8+ T cells within breast tumors, facilitated the accumulation of CD8+ T cells at the tumor margins, decreased tumor size, and reduced incidence of lung metastases." (PMID 37860188, 2023). "By using single-cell RNA sequencing (scRNAseq) analyses we show that TOP2A multi-peptide vaccination induces anti-tumor CD4 + Th1 cells and cytotoxic CD8 + T cells in mouse breast tumor and lymph node tissue samples." (PMID 37880313, 2023). "Immunophenotyping the CD45RO-expressing lymphocytes infiltrating breast tumor tissues revealed that the majority of CD45RO+ lymphocytes displayed the CD3 pan T-cells marker (more than 90%), followed by CD8+, CD4+, and CD16+/CD56+ NK cells." (PMID 37835465, 2023). "We verified this by LC-MS analysis of adenosine and immunostaining of CD4, CD39, CD206 and CD73 expression in an orthotopic breast tumour model by inoculating firefly luciferase-transfected 4T1 (fLuc-4T1) tumour cells into the breast pads of BALB/c mice." (PMID 35918337, 2022). "Flow cytometry analysis of PyMt cell line-derived breast tumors and tumor-draining lymph nodes from Tslptg and WT mice revealed increased CD4+ T cells, especially GATA3+ CD4+ T cells in Tslptg compared with WT mice." (PMID 36467403, 2022). "Of these, 262 women (training cohort) had breast tumor IHC for four classic immune cell markers (CD8, CD4, CD20, and CD163)." (PMID 36376974, 2022). "The transferred CD4+ T cells became highly proliferating GATA3+ CD4+ T cells in the tumor-draining lymph nodes and breast tumors of Tslp-PyMttg Rag1KO mice." (PMID 35657353, 2022). "Collectively, SI-2 treatment also recruited cytotoxic immune cells (CD4 + T cells and NK cells) and then generated a tumor-suppressing TIME to suppress 4T1 breast tumor progression in immune-intact female mice." (PMID 36316775, 2022). "CD4+, CD8+ and IL-2+ (p<0.05 for all) cells infiltration was also significantly increased in the breast tumor microenvironment of F3-treated mice compared with the tumors of untreated mice." (PMID 35972917, 2022). "We found that pharmacological inhibition of cPLA2 reduced breast tumor growth and metastasis with a decreased abundance of only CTLA4+ CD4+ T cells and M2-TAMs." (PMID 35135586, 2022). "IHC analysis revealed that the levels of CD4 + T cells, CD8 + T cells, and NK cells were significantly elevated in SRC-3 KD E0771 breast tumors compared to the control E0771 breast tumors." (PMID 36316775, 2022). "Below we describe the phenotypes and spatial position of CD8+ (effector) T cells, CD4+ T cells, regulatory T cells, B cells and natural killer cells within the TME of breast tumors with a focus on TNBC." (PMID 33467084, 2021). "In highly malignant 4T1 breast tumors, posttreatment supplementation with sEVs released after therapy could effectively orchestrate the differentiation of MDSCs and monocytes into macrophages and CD4+ T cells toward the Th1 subtype; thus, enhancing the efficacy of cryo-thermal therapy." (PMID 34681680, 2021). "Our study showed that CD45 immune cells were partially positive in breast tumor tissues, naive T cell marker CD3 was inhibited, and CD4, CD8, and NK1.1 were also inhibited." (PMID 34659411, 2021). "Here, we investigated the effects of the different ICIs on expanded T cell populations (both CD4+ and CD8+ T cells) after nine days in human breast tumor explant culture." (PMID 32616706, 2020).
breast tumor (continued). "We focused on immune cell types, especially the CD4+/CD8+ T cells, and discovered differences between breast tumor tissues and adjacent normal tissues with polarized enrichment of certain cell types." (PMID 32728493, 2020). "This work revealed that NAC treatment can substantially downregulate CD4+ and upregulate CD8+ T cell ICP expression as well as deplete the amount of TILs and CD8+ T cells found in breast tumor samples." (PMID 32429929, 2020). "EGCG ameliorated immunosuppression by significantly decreasing the accumulation of myeloid-derived suppressor cells (MDSCs) and increasing the proportions of CD4+ and CD8+ T cells in spleen and tumor sites in 4T1 breast tumor-bearing mice." (PMID 32290071, 2020). "ARHGEF binds to CD44 protein, resulting in cytokine production and breast tumor progression, whereas CD44 binds to FAK in the context of cellular activation in Hela-CD4 cells." (PMID 31501460, 2019). "For the first time, this study demonstrates that inhibition of V-ATPase expression in HSC leads to a decrease in CD4+ and CD8+ T cell populations and thus promotes breast tumor growth and metastasis." (PMID 30237863, 2018). "We also used immunofluorescence microscopy to analyze serial breast tumor sections stained for CD3 and CD4, and either CD45RA (naive CD4+ T cells) or Foxp3 (Tregs)." (PMID 28290464, 2017). "We observed markedly increased CD4/CD8 ratios at late tumor stages compared with those in the early tumor stages in both 4T1 and E0771 breast tumor models." (PMID 25968569, 2015). "As expected, markedly increased CD4/CD8 ratios at the late tumor stages were observed compared with those in the early tumor stages in both 4T1 and E0771 breast tumor models." (PMID 25968569, 2015). "CCL5 mediates breast tumor progression and recurrence by interacting with the CCR3 axis, recruiting macrophages and regulating the CD4+/CD8+, CCR5+/CD4+ or Treg/CCR5+ cell ratios." (PMID 37051596, 2023). "In addition, inoculation with Fn suppresses the accumulation of tumor-infiltrating T cells and promotes tumor progression, resulting in fewer CD4+ and CD8+ T cells in breast tumor-bearing mice." (PMID 37723150, 2023). "In the 4T1 murine breast tumor model, PLP could control the size of breast tumors and improve immunity by recruiting DCs, macrophages, and CD4+ and CD8+ T cells in the tumor microenvironment." (PMID 34504423, 2021). "Together, our results indicate that a short course of denosumab enhances immune infiltration as determined by the increased levels of TILs, B and T lymphocytes, and CD4+ and CD8+ T cells in luminal and HER2+ breast tumors, validating the clinical relevance of the findings in the preclinical models." (PMID 33303745, 2020). "PD1 expression was high in all of the tumor infiltrating T cells that were analyzed (>60.22 of all CD4+ or CD8+ T cells) suggesting exhaustion of these infiltrating cells and a potential role for checkpoint therapy in breast tumors with pre-existing infiltrating T cells." (PMID 31417550, 2019). "Together, these results show that effective low-dose Anlotinib combined with anti-PD-1 therapy induces tumor vascular normalization and increases the proportions of CD4+ T, CD8+ T, and NK cells in EO771 breast tumors, which may, in turn, contribute to enhanced antitumor effects." (PMID 35990640, 2022). "Moreover, the synthetic resveratrol analog HS-1793 was also shown to decrease the CD4+CD25+ Treg cell population in FM3A breast tumor-bearing mice without affecting the CD4+ T cell population." (PMID 33572626, 2021). "Additionally, ursolic acid carried by liposomes could also effectively reduce tumor CD4+ CD25+ Foxp3+ T cells and MDSCs in 4T1 breast tumor-bearing mice." (PMID 33572626, 2021).
breast tumor (continued). "In a multivariable analysis high breast tumor median CXCL13 content was independently associated with favorable DDFS (HR 0.44, 95% CI 0.29–0.67; P ≤ 0.001), whereas CD4 content and FOXP3 content were not (HR 1.89, 95% CI 0.80–1.78; P = 0.396; and HR 1.20, 95% CI 0.78–1.84; P = 0.400, respectively)." (PMID 29482642, 2018). "Six immune cell populations were detected in the breast tumor samples including CD8 + T cells, CD4 + T cells, CD4/CD8 double-negative T cells (DNT), dendritic cells (DC), macrophages and neutrophils." (PMID 37880313, 2023).
adult T-cell leukemia/lymphoma (123 papers, 2005 to 2025). A peripheral (mature) T-cell neoplasm linked to the human T-cell leukemia virus type 1 (HTLV-1), adult T-cell leukemia/lymphoma is endemic in several regions of the world, in particular Japan, the Caribbean, and parts of Central Africa. "It primarily targets CD4+ T-cells, causing severe diseases such as adult T-cell leukemia/lymphoma (ATLL) and HTLV-1-associated myelopathy/tropical spastic paraparesis (HAM/TSP)." (PMID 41472303, 2025). "Adult T-cell leukemia–lymphoma (ATL) is a mature peripheral CD4+ T-cell malignancy caused by infection with human T-lymphotropic virus type I (HTLV-1)." (PMID 38247820, 2024). "Adult T-cell lymphoma (ATL) is a hematological malignancy of CD4+ mature T-lymphocytes commonly associated with chronic human T-lymphotropic virus type I (HTLV-1) infection." (PMID 37529824, 2023). "Adult T cell leukemia/lymphoma (ATLL) is a CD4-positive peripheral T cell lymphoma caused by human T cell lymphotropic virus type 1 (HTLV-1)." (PMID 36181532, 2023). "HTLV-1 is an enveloped complex retrovirus and the causative agent of an aggressive neoplasm of mature CD4+CD25+ T-cells known as adult T-cell leukemia/lymphoma (ATLL)." (PMID 37242405, 2023). "Human T-cell leukemia virus type 1 (HTLV-1), a retrovirus which mainly infects CD4+ T cells and causes adult T-cell leukemia/lymphoma (ATL), is primarily transmitted via direct cell-to-cell transmission." (PMID 36300109, 2022). "Diseases caused by HTLV-1 include an aggressive CD4+ lymphoproliferative malignancy, designated adult T-cell leukemia lymphoma (ATLL) and spastic paraparesis, known as HTLV-1 myelopathy (HAM) or tropical spastic paraparesis (TSP)." (PMID 36159878, 2022). "Adult T-cell leukemia/lymphoma (ATLL) is an aggressive malignancy of CD4+ T-cells associated with HTLV-1 infection." (PMID 34685494, 2021). "HTLV-1 is the causative agent of a neoplasm of CD4+CD25+ T cells known as adult T-cell leukemia/lymphoma (ATLL), which consists of four clinical subtypes: smoldering, chronic, lymphoma, and acute." (PMID 32645846, 2020). "Adult T cell leukemia/lymphoma (ATLL) is a hematological malignancy caused by clonal proliferation of CD4+ T cells infected with human T cell leukemia virus type 1 (HTLV-1)." (PMID 33313334, 2020). "HTLV-1 resides mainly in CD4+ T lymphocytes and causes adult T cell leukemia/lymphoma (ATL), a CD4+ T cell malignancy, in some 5% of HTLV-1-infected individuals." (PMID 31738810, 2019). "Adult T-cell leukemia/lymphoma (ATL) is an aggressive malignancy of CD4+CD25+ lymphocytes caused by human T-cell lymphotropic virus type 1." (PMID 24890041, 2014). "Adult T-cell leukemia (ATL) is an aggressive malignancy of CD4+ T-cells caused by human T-cell leukemia virus type 1 (HTLV-1)." (PMID 21414204, 2011). "Adult T-cell Leukemia/Lymphoma (ATL) is a CD4+ T-cell malignancy caused by infection with HTLV-1." (PMID 40256740, 2025). "Human T cell leukemia virus type 1 (HTLV-1) is a retrovirus with preferential CD4+ T cell tropism that causes a range of conditions spanning from asymptomatic infection to adult T cell leukemia and HTLV-1–associated myelopathy (HAM), an inflammatory disease of the CNS." (PMID 38193535, 2024). "HTLV-1 infection is associated with two major diseases: a malignancy of mature CD4+ T-cells named adult T-cell leukemia/lymphoma (ATLL), and HTLV-1-associated myelopathy/tropical spastic paraparesis (HAM/TSP), with 1–5% of infected individuals developing related diseases." (PMID 36298702, 2022). "Adult T-cell leukemia (ATL) is a CD4+ T-cell neoplasm caused by human T-cell leukemia virus type I. As the prognosis for patients with ATL remains extremely poor due to resistance to conventional chemotherapy regimens, introduction of novel therapeutic agents is needed." (PMID 33167425, 2020).
adult T-cell leukemia/lymphoma (continued). "Human T-cell leukemia virus type 1 (HTLV-1) is an oncogenic human retrovirus that transforms CD4+ T-cells and causes a variety of diseases including adult T-cell leukemia/lymphoma (ATL) and a neurodegenerative disease called HTLV-1-associated myelopathy/tropical spastic paraparesis (HAM/TSP)." (PMID 33425776, 2020). "Human T-cell leukemia virus type 1 (HTLV-1) is the causal agent of a neoplastic disease of CD4+ T cells, adult T-cell leukemia (ATL), and inflammatory diseases including HTLV-1 associated myelopathy/tropical spastic paraparesis, dermatitis, and inflammatory lung diseases." (PMID 21347344, 2011). "Human T-cell leukemia virus type 1 (HTLV-1) was discovered as the first human retrovirus and shown to be etiologically associated with a highly aggressive mature CD4+ T cell malignancy, adult T-cell leukemia/lymphoma (ATLL)." (PMID 34771703, 2021). "Adult T-cell leukemia/lymphoma (ATLL) is an aggressive neoplasm of CD4+ T cells linked to human T-cell leukemia virus type 1 (HTLV-1) infection." (PMID 33670114, 2021). "Among them, the most carcinogenic agent is HTLV-1, which causes adult T-cell leukemia/lymphoma (ATLL), a malignancy of mature CD4+ T-cells." (PMID 31835460, 2019). "Adult T-cell leukemia/lymphoma (ATLL) is a malignancy of CD4+ T-cells associated with human T-cell leukemia virus type 1 (HTLV-1) infection." (PMID 30837480, 2019). "Adult T-cell Leukemia/Lymphoma (ATLL) is classified as a peripheral CD4+ T-cell neoplasm caused by the human T-cell lymphotropic virus type 1 (HTLV-1)." (PMID 28559645, 2017). "Adult T-cell leukemia/lymphoma (ATLL) is an aggressive lymphoproliferative disease associated with infection of CD4 T cells by the Human T-cell Leukemia Virus Type 1 (HTLV-I)." (PMID 26170835, 2015). "Human T-cell leukemia virus type 1 (HTLV-1) is a complex retrovirus that infects CD4+ T cells and causes adult T-cell leukemia/lymphoma (ATLL) in 3%–5% of infected individuals after a long latent period." (PMID 25341660, 2014). "HTLV-1 is the etiological agent of Adult T-cell Leukemia/Lymphoma (ATLL), a malignant lymphoproliferation of T CD4+ cells and of HTLV-1 Associated Myelopathy/Tropical Spastic Paraparesis, a chronic neurological inflammatory disease (HAM/TSP)." (PMID 22911729, 2012). "Human T-cell leukemia virus type 1 (HTLV-1) is the pathogen that causes adult T-cell leukemia/lymphoma (ATLL), which is a unique malignancy of CD4+ T cells." (PMID 23762762, 2012). "Human T-cell leukemia virus type 1 (HTLV-I) is a complex retrovirus that causes adult T-cell leukemia/lymphoma (ATLL), a CD4 lymphoproliferative disease." (PMID 16822311, 2006). "The viruses present tropism for CD4+ and CD8+ T cells and are currently associated with adult T-cell leukemia/lymphoma (ATLL) and inflammatory diseases like HTLV-1-associated myelopathy (HAM), uveitis, infective dermatitis, arthritis, and other illnesses." (PMID 40573355, 2025). "Adult T-cell leukemia–lymphoma (ATL) is caused by human T-lymphotropic virus type I (HTLV-1) and is characterized by the proliferation of malignant peripheral CD4+ T cells." (PMID 38247820, 2024). "The peripheral T-cell malignancy that arises from CD4-positive T cells that are latently infected with the human T-cell leukemia virus (HTLV) type 1 is still referred to as adult T-cell leukemia/lymphoma (ATLL) by both ICC and WHO-HAEM5." (PMID 37762472, 2023). "Adult T-cell lymphoma/leukemia (ATLL) affects the mature CD4 and CD25 lymphocyte lineage and has one of the poorest prognosis among hematologic malignancies." (PMID 36841815, 2023). "Human T-cell leukemia virus type 1 (HTLV-1) is the infectious cause of adult T-cell leukemia/lymphoma (ATL), an extremely aggressive and fatal malignancy of CD4+ T-cells." (PMID 36819050, 2023). "HTLV-1 is known to cause adult T-cell leukemia (ATL), an aggressive cancer of peripheral CD4 T cells; however, it is also responsible for HTLV-1-associated myelopathy/tropical spastic paraparesis (HAM/TSP)." (PMID 37108125, 2023).